YTHDF2 (YTH N6-methyladenosine RNA binding protein F2)
Diseases named in the same sentence as YTHDF2 in open-access papers (continued):
Sharing a sentence is not in itself a finding about the gene and the disease.
liver cancer (continued). "Given that the important role of hypoxia in tumor development, our research group has long focused on the role of hypoxia in liver cancer, and METTL3 YTHDF2 and METTL14 has been studied more frequently in liver cancer." (PMID 35982895, 2022). "Recent studies discovered that YTHDF2 upregulation can inhibit ERK and MEK activation within liver cancer cells." (PMID 36277978, 2022). "It has been shown that YTHDF2 targets a plethora of mRNAs for degradation in cancers, such as, TNFR2, c-Myc and CEBPA in leukemia, EGFR, IL11, SERPINE2 and SOCS2 in liver cancer, and PD-1, CXCR4, and SOX10 in melanoma." (PMID 33658012, 2021). "METTL14 promotes SOCS2 expression to inhibit the progression of liver cancer, while METTL3 inhibits SOCS2 expression in a YTHDF2-dependent manner, but whether METTL3 regulates the metabolism of HCC through SOCS2 requires more direct evidence." (PMID 38560499, 2024). "Interestingly, luciferase assays and polysome profiling found that YTHDF2 retained the m6A methylation of the 5'-UTR of OCT4 mRNA, resulting in enhanced protein expression, thereby promoting liver cancer progression." (PMID 35382893, 2022). "Mechanistically, YTHDF2 could regulate m6A methylation of OCT4 mRNA and thus promote the liver cancer stem cell phenotype and HCC metastasis." (PMID 34539889, 2021). "Similarly, in liver cancer, YTHDF2 modulated the m6A methylation of OCT4 mRNA and promoted the metastasis of liver cancer stem cells." (PMID 34345203, 2021). "However, this study only found changes in the expression of the reading protein YTHDF2 in liver cancer and did not address the role of m6A in liver cancer." (PMID 35155557, 2022).
pancreatic cancer (64 papers, 2018 to 2025). "Substantial evidence has revealed that YTHDF2 is intimately associated with tumor cell proliferation and metastasis, and its pivotal role in the post-transcriptional regulation of pancreatic cancer 15-17." (PMID 40756353, 2025). "In contrast to pancreatic cancer, YTHDF2 enhances cell motility and is associated with tumor metastasis in prostate cancer." (PMID 32612834, 2020). "The expression of YTHDF2 is up‐regulated in pancreatic cancer and significantly associated with tumour stage." (PMID 33029866, 2020). "Given that EMT serves as the mechanism underlying VM, it is speculated that YTHDF2 may inhibit VM in pancreatic cancer by suppressing the Hippo pathway." (PMID 39098905, 2024). "YTHDF2 also regulates the epithelial–mesenchymal transition (EMT) via the downregulation of total yes-associated protein (YAP) mRNA which has been reported to be closely related to the EMT in pancreatic cancer cells." (PMID 33162550, 2020). "More importantly, we found that THM specifically binds to YTHDF2 as a direct cellular target to block the proliferation of pancreatic cancer cells." (PMID 40756353, 2025). "The FTO-mediated upregulation of platelet-derived growth factor C (PDGFC) autocrine signaling through the m6A/YTHDF2 axis drives pancreatic cancer progression." (PMID 40986143, 2025). "We further investigated the drug-target binding affinity of YTHDF2 in pancreatic cancer cells by immunofluorescence staining using Cy5-labeled THM (THM-Cy5)." (PMID 40756353, 2025). "YTHDF2, on the other hand, induces mRNA degradation by binding to the m6A modification site and is significantly increased in pancreatic cancer tissues, with levels much higher in patients with advanced disease." (PMID 37928762, 2023). "All of the results above indicate that m6A modification mediated by the demethylase FTO and the reader YTHDF2 plays an important role in maintaining the stability of LINC01134 in pancreatic cancer cells as well as relates to the high expression of LINC01134." (PMID 37914721, 2023). "The knockout of YTHDF2 inhibits the proliferative ability of pancreatic cancer cells, although the invasive and metastatic abilities and EMT are enhanced, possibly due to different modes of action." (PMID 35155557, 2022). "In pancreatic cancer, YTHDF2 promoted cell growth through activation of the AKT/GSK3β/CCND1 pathway." (PMID 35350378, 2022). "Studies have found that both the mRNA and protein levels of YTHDF2 in pancreatic cancer tissues are significantly higher than those in paratumor tissues, and the expression of YTHDF2 tends to increase as the stage of the disease advances." (PMID 35155557, 2022). "In pancreatic cancer, YTHDF2 was involved in a “migration-proliferation dichotomy” wherein YTHDF2 promoted proliferation but inhibited migration by suppressing YAP signaling, an EMT-promoting signaling pathway." (PMID 35350378, 2022). "The expression of YTHDF2 was higher in pancreatic cancer tissue than that in precarcinomatous tissue." (PMID 35941702, 2022). "Compared with normal tissues, both the protein and mRNA levels of YTHDF2 were upregulated in pancreatic cancer tissues, and the knockdown of YTHDF2 can increase YAP expression levels and inhibit TGF‐β/Smad signalling." (PMID 34647424, 2022). "YTHDF2 expression is upregulated at both the mRNA and protein levels in pancreatic cancer in humans and serves as an independent factor predicting a high stage in patients." (PMID 34246319, 2021). "Surprisingly, YTHDF2 promotes migration in prostate cancer in vitro, while the opposite has been investigated in the case of pancreatic cancer." (PMID 34521394, 2021). "Consistently, inhibition of YTHDF2 expression in pancreatic cancer cells suppresses proliferation and colony formation, highlighting an oncogenic role for YTHDF2 in PDAC." (PMID 33855021, 2021). "In pancreatic cancer cells, YTHDF2 orchestrates epithelial–mesenchymal transition/proliferation dichotomy." (PMID 34187307, 2021).
pancreatic cancer (continued). "YTHDF2 was found upregulated in pancreatic cancer which promoted cancer cell proliferation via activation of Akt/GSK3β/Cyclin D1 pathway." (PMID 33814008, 2021). "One research found that YTHDF2 participated in the progression of pancreatic cancer via collaborating with ALKBH5, a pivotal demethylase of m6A." (PMID 33593354, 2021). "YTHDF2 can be used as a new marker of pancreatic cancer, but the specific mechanism needs to be clarified." (PMID 33692959, 2021). "The loss of ALKBH5 post-transcriptionally decreased the expression of PER1 in YTHDF2-dependent manner, and facilitated cell migration, invasion, proliferation and tumor growth in pancreatic cancer." (PMID 33593354, 2021). "Previous studies reported that METTL3, METTL14, FTO, ALKBH5 and YTHDF2 play important roles in pancreatic cancer cells." (PMID 34458141, 2021). "In pancreatic cancer, the expression level of YTHDF2 increases with the extension of the cancer stage, which can inhibit epithelial-mesenchymal transition by inhibiting YAP signaling." (PMID 33552994, 2020). "For example, upregulated YTHDF2 is found in pancreatic cancer, increased m5C is detected in lung cancer and accumulated Ψ contributes to the advancement of prostate cancer." (PMID 32303268, 2020). "Studies have shown that knockdown of YTHDF2 expression inhibits cell proliferation and promotes the migration and invasion of pancreatic cancer cells." (PMID 33344502, 2020). "Another study found that YTHDF2 was overexpressed in pancreatic cancer and related to patients' poor prognosis." (PMID 33102202, 2020). "Thereafter, Chen and colleagues reported that YTHDF2 was highly expressed in pancreatic cancer, which promoted the proliferation and inhibited the migration and invasion of pancreatic cancer cells." (PMID 32111180, 2020). "A previous study reported that METTL3, ALKBH5 and YTHDF2 play important roles in pancreatic cancer cells." (PMID 32843065, 2020). "Surprisingly, YTHDF2 also has the ability to inhibit the migration of cancer cells in pancreatic cancer." (PMID 32612834, 2020). "In pancreatic cancer, knockdown of YTHDF2 expression inhibits cell proliferation and promotes the migration and invasion of cells." (PMID 33344502, 2020). "Chen and colleagues found that the expression level of YTHDF2 in pancreatic cancer tissues is higher than that in normal tissues at the mRNA and protein levels; moreover, YTHDF2 is an independent influencing factor for the deterioration of patients’ condition." (PMID 31810483, 2019). "In pancreatic cancer cells, YTHDF2 serves as a suppressor in adhesion, invasion, migration and EMT through YAP signaling, but YTHDF2 acts as a promoter in proliferation via Akt/GSK3b/CyclinD1 pathway." (PMID 30062093, 2018). "High expression of YTHDF2 mRNA and protein in pancreatic cancer have a positive correlation with its progression." (PMID 30062093, 2018). "In addition, to confirm that YTHDF2 is the dominant THM-target protein in the THM-induced cell death in pancreatic cancer cells, we generated stable cell lines overexpressing YTHDF2 by lentiviral infection." (PMID 40756353, 2025). "Our study showed that THM decreases YTHDF2 protein levels in pancreatic cancer cells." (PMID 40756353, 2025). "In pancreatic cancer, inhibition of YTHDF2 increases YAP expression and promotes EMT." (PMID 39098905, 2024). "The overexpressed YTHDF2 binds to m6A-modified yes-associated protein 1 (YAP) mRNA, inhibiting YAP expression and promoting the migration-proliferation dichotomy and epithelial-mesenchymal transition of pancreatic cancer cells." (PMID 38856795, 2024). "YTHDF2 expression is upregulated at both the mRNA and protein levels in pancreatic cancer tissues, and its expression is higher in late-stage clinical patients with pancreatic cancer." (PMID 39062595, 2024). "Among the YTHDF family, YTHDF2 is the most studied protein in pancreatic cancer." (PMID 36999016, 2023).
pancreatic cancer (continued). "YTHDF2 is elevated in pancreatic cancer and orchestrates the migration/proliferation dichotomy." (PMID 36999016, 2023). "Interestingly, in pancreatic cancer cells, a phenomenon called the “migration-proliferation dichotomy” has been observed: in this case, YTHDF2 promotes proliferation but inhibits migration and invasion." (PMID 35186724, 2022). "Interestingly, the reader YTHDF2 was found to inhibit invasion and migration in pancreatic cancer, but facilitate the migration of prostate cancer in vitro." (PMID 33796449, 2021). "Furthermore, YTHDF2 orchestrated two cellular processes, including promoting proliferation and suppressing migration and invasion in pancreatic cancer cells, a phenomenon called the “migration-proliferation dichotomy”." (PMID 34239358, 2021). "Similarly, overexpression of the m6A reader YTHDF2 has been reported in pancreatic cancer, particularly in patients at later stages of cancer progression." (PMID 33855021, 2021). "Interestingly, YTHDF2 predominantly binds to PIK3CB [G] compared to PIK3CB [T] in pancreatic cancer cells." (PMID 34239358, 2021). "However, YTHDF2 overexpression also suppressed the migration and invasive capability of pancreatic cancer cells, an effect termed ‘migration-proliferation dichotomy’." (PMID 33814008, 2021). "YTHDF2 may be an indicator of the diagnosis and prognosis of pancreatic cancer, and YTHDF2 has potential value as a new target for the prevention and treatment of pancreatic cancer." (PMID 34246319, 2021). "A study on pancreatic cancer demonstrated the high expression of YTHDF2." (PMID 33692959, 2021). "YTHDF2 has the dual function of promoting and inhibiting the progression of pancreatic tumours." (PMID 34246319, 2021). "Interestingly, YTHDF2 has dual functions in pancreatic cancer by promoting proliferation and restraining migration and invasion." (PMID 32733931, 2020). "One example is that YTHDF2, an m6A reader, may promote the proliferation of pancreatic cancer cells, whereas it suppresses metastasis in pancreatic cancer." (PMID 32760220, 2020). "YTHDF2 has a reverse regulatory effect on cell proliferation and invasion in pancreatic cancer." (PMID 33029866, 2020). "Interestingly, the reader YTHDF2 was suggested to facilitate the migration of prostate cancer in vitro but inhibit invasion and migration in pancreatic cancer." (PMID 32038982, 2020). "The relationship between YTHDF2 and YAP in pancreatic cancer cells needs further exploration, especially whether the reverse regulation of YTHDF2 exists in other tumours." (PMID 33029866, 2020). "The overexpression of FTO, IGF2BP2 and YTHDF2 are related to the pancreatic cancer." (PMID 32612834, 2020). "Additionally, YTHDF2 has the dual effect of promoting the proliferation and inhibiting the migration and invasion of pancreatic cancer cells; this effect is called the “migration proliferation dichotomy”." (PMID 33162550, 2020). "Therefore, YTHDF2 as a target for pancreatic cancer still needs serious consideration." (PMID 39062595, 2024). "Notably, YTHDF2 has an important role in the regulatory effects of m6A methylases and demethylases on the tumorigenicity of osteosarcoma, breast tumors, melanoma, bladder cancer, pancreatic cancer, and colorectal cancer." (PMID 33795663, 2021). "Moreover, the expression of YTHDF2 is up-regulated in pancreatic cancer." (PMID 32612834, 2020). "Targeting YTHDF2 is a critical determiner for THM-induced autophagic cell death and the immunosensitizing effect of THM with anti-PD-1 inhibitor in pancreatic cancer." (PMID 40756353, 2025). "Therefore, targeting YTHDF2 may be a highly promising approach for pancreatic cancer treatment." (PMID 40756353, 2025). "However, it is unclear whether YTHDF2 mediates pancreatic cancer growth in an m6A-dependent manner." (PMID 35350378, 2022).
pancreatic cancer (continued). "For instance, YTHDF2 orchestrated two cellular processes via TGF-β/Smad signaling pathway: promoted proliferation and inhibited migration and invasion in pancreatic cancer cells." (PMID 35046996, 2021). "Meanwhile, upregulation of YTHDF2 destabilizes YAP mRNA by initiating the AKT/GSK3β/cyclin D1 pathway, which promotes proliferation and inhibits the migration of pancreatic cancer." (PMID 32303268, 2020). "In pancreatic cancer, YTHDF2 regulates the EMT (epithelial-mesenchymal transition, EMT) process of pancreatic cancer cells through the YAP signaling pathway." (PMID 33505426, 2020). "The reader YTHDF2 and the eraser FTO promotes cancer cell proliferation in pancreatic cancer and glioma." (PMID 32850303, 2020). "Interfering of YTHDF2 upregulates the expression of MMP2 and MMP9 that possess the capability to promote cell adhesion, thus enhancing the invasion and adhesion of pancreatic cancer cells." (PMID 31959747, 2020). "YTHDF2 and METTL3 have previously been reported as tumor suppressors in HCC, and as oncogenes in pancreatic cancer and acute myelocytic leukemia." (PMID 32391046, 2020). "Mechanistically, we found that THM mediated the post-transcriptional regulation of autophagy activation by targeting YTHDF2, thereby preventing the reading of the m6A modifications of ATG5 and ATG7 mRNAs, ultimately resulting in autophagic death in pancreatic cancer cells." (PMID 40756353, 2025). "Interestingly, this study found that YTHDF2 plays a different role in the proliferation, invasion, metastasis and EMT of pancreatic cancer cells." (PMID 35155557, 2022). "The analysis of the clinical relationship between YTHDF2 and pancreatic cancer was based only on a database analysis without any actual verification, and no in vivo studies were performed." (PMID 35155557, 2022). "In addition, YTHDF2 was dysregulated in human cancers, including bladder cancer, HCC, gastric cancer, breast cancer, osteosarcoma, cervical cancer, prostate cancer, pancreatic cancer, acute myeloid leukemia (AML) and so on." (PMID 33593354, 2021). "YTHDF2 inhibited adhesion, invasion, migration, and Epithelial-Mesenchymal Transition (EMT) through the YAP signal and promoted the proliferation of pancreatic cancer cells through the Serine/threonine-protein kinases/Glycogen synthase kinase 3 beta/Cyclin D1 (AKT/GSK3B/CCND1) pathway." (PMID 33692959, 2021). "Contrasted to that in pancreatic cancer cells, the expression of Mmp2 did not change, and Mmp9 was downregulated by Ythdf2-KO in spermatogonia." (PMID 31959747, 2020). "YTHDF2 has an influence on EMT by YAP signaling, which finally leads to the pancreatic cancer." (PMID 32612834, 2020). "One function of YTHDF2 is to coordinate the “migration and proliferation dichotomy,“ involving the promotion of the proliferation of pancreatic cancer cells and simultaneous inhibition of their migration and invasion; the other is to regulate EMT of pancreatic cancer cells." (PMID 34246319, 2021). "Analysis of protein expression data from the Proteomic Data Commons database revealed a negative correlation between YTHDF2 and HMGB1 protein expression in pancreatic cancer samples." (PMID 40495163, 2025).